IL1B (interleukin 1 beta)
Diseases named in the same sentence as IL1B in open-access papers (continued):
Sharing a sentence is not in itself a finding about the gene and the disease.
tumor (continued). "Interestingly, the pro-inflammatory cytokine IL-1B and its receptor IL1R1 were increased in bone metastases compared with primary tumours in ER+ BB2RC08 cells but appeared to decrease in ER-ve BB6RC37 cells, and similar pattern was observed with the cell-cell adhesion molecule γ Catenin." (PMID 31783893, 2019). "All these data seem to indicate that the non-expression of pro-inflammatory cytokines (such as IL-1β and IL-6), together with the expression of an anti-inflammatory cytokine (such as IL-10) could contribute to tumor immune escape." (PMID 31086100, 2019). "Our data support the hypothesis that not all IL-1β signalling is involved in tumour promotion, as IL-1β is capable of stimulating caspase-11 expression, which can subsequently mediate STAT1 activation in IECs." (PMID 30538296, 2019). "In addition, we showed that IL-1β promoted EMT and metastasis of PDAC cells, and that the use of celecoxib could sensitise tumour cells to gemcitabine." (PMID 31588122, 2019). "rIL-17A notably enhanced the in vitro production of IL-1β and IL-23 by primary keratinocytes at both the mRNA and protein levels, suggesting that IL-17A is an important factor to enhance epidermal IL1/23 production in the epidermis around wounds after skin injury." (PMID 29483920, 2018). "Furthermore, IL-1β induced CCL2 expression in macrophages and tumor cells." (PMID 30042333, 2018). "In addition to intrinsic, IKKα also mediated IL-1β-inducible NF-κΒ activity of KRASMUT tumor cells, since shChuk but not shIkbkb abolished IL-1β-induced NF-κB activity across KRASMUT cell lines." (PMID 29445180, 2018). "However, our work revealed a new mechanism for tumour-secreted IL-6 and IL-8, but not common inflammatory cytokines such as TNFα and IL-1β secreted by immune cells, to promote tumour cell migration and metastasis." (PMID 28548090, 2017). "When inflammation occurs, tumor cells, macrophages, and other tumor infiltrating immune cells possess high reactive oxygen species (ROS), and secrete chemokines and cytokines such as IL-6, tumor necrosis factor (TNF)-α, IL-1β, IL-10, and transforming growth factor (TGF)-β to tumor microenvironment." (PMID 28629173, 2017). "Given that blockade of NLRP3 inflammasome could delay tumorigenesis in SCCHN mice by reducing the production of IL-1β, and the stimulation on NLRP3 inflammasome from early tumor is less than advanced tumor, which might account for the decreased expression of NLRP3 and pro-Caspase-1." (PMID 28865486, 2017). "Moreover, when binding to P2X7 receptors on DCs, ATP stimulates the assembly of NLRP3 inflammasome, and initiates a series of downstream events that ultimately result in the production and release of IL-1β, a cytokine required for the priming of IFN-γ producing tumor-specific CD8+ T cells." (PMID 26881822, 2016). "Our preliminary data show that tumor growth was not reduced in IL-18 KO mice, indicating that IL-1β and IL-18 may have different or even opposite roles in tumor development (Guo, unpublished results)." (PMID 27786298, 2016). "As B16 cells do not make IL-1, non-malignant cells in/around the tumour (e.g. stromal cells, fibroblasts and/or macrophages) may represent the source of IL-1β." (PMID 27100888, 2016). "However, in mice given CTX plus MAA (D1.0 and D2.0 groups), there was increased Bax expression, decreased Bcl-2 and Bcl-1 expression, increased caspase-3 expression, and slower tumor growth, but no alteration in IL-1β expression." (PMID 27043621, 2016). "Anakinra did not increase tumour cell apoptosis but reduced proliferation and angiogenesis in addition to exerting significant effects on the tumour environment reducing bone turnover markers, IL-1B and TNF alpha." (PMID 27765923, 2016).
tumor (continued). "In subsequent studies, other groups were able to demonstrate that IL-1β is indeed a crucial mediator in PDT outcome and neutrophilia since blocking of this cytokine led to a significantly decreased rate of tumor cures and neutrophils in the tumor-draining lymph nodes (TDLN) in response to treatment." (PMID 27782066, 2016). "Although IL-1β was not applied during in vivo tumor formation, many innate inflammatory cells, including macrophages and myeloid-derived suppressor cells (MDSCs) were recruited to the tumor sites in the host mice (data not shown)." (PMID 27609180, 2016). "Likewise, chemokines and cytokines are extensively produced in the tumor microenvironment regardless of the initial triggers, and mediators such as IL-1β, TNFα, CCL2 and IL-6 directly promote tumor progression in experimental models of CRC." (PMID 27494857, 2016). "Moreover, wogonoside inhibited the mRNA levels of IL-1β, IL-6 and TNF-α in tumor tissues." (PMID 27102438, 2016). "By contrast, as IFN-γ-treated tumors contained high levels of endogenous cytokines TNF-α, IL-12p70 and IL-1β and the tumor-infiltrating macrophages did not express putative M2 marker CD206, we find it likely that IFN-γ instead skewed the macrophages towards M1 phenotype." (PMID 26107883, 2015). "Furthermore, using anti-IL-1β blocking antibodies, chemotherapy induced IL-1β was shown to be required for the recruitment of IL-17-producing γδ T cells and generation of IFN-γ-producing tumor-specific CD8 T cells." (PMID 26486085, 2015). "Moreover, we found that IL-1β cytokine was significantly increased in tumor masses but not at the systemic level, thus resulting tightly correlated to the tumor site." (PMID 26158862, 2015). "Furthermore, antibodies against the IL-1β and TNF-α receptors, which were added to the media conditioned by macrophages and tumor cells, were found to inhibit the enhancement of VEGF-C expression in macrophages co-cultivated with tumor cells." (PMID 25120672, 2014). "However, TAMs from several tumor models also exhibit typical M1 cytokines such as TNF-α and IL-1β." (PMID 25071759, 2014). "Moreover, the increased expression of IL-1α, IL-1β, VEGF-A, VEGF-C, and VEGF-D in tumor stromal cells, including macrophages, suggests a mechanism by which tumor growth, angiogenesis, lymphangiogenesis, and lymph node metastasis are enhanced in highly metastatic cancer cells." (PMID 24924428, 2014). "Indeed, the absence of IL-1β in the tumor microenvironment limited the recruitment of FGF1-producing mononuclear cells to tumor sites." (PMID 24734023, 2014). "Therefore WP1066 inhibition of STAT3 activity and tumour progression was due in part to reduced polymophonuclear infiltration and reduced STAT3-dependent transcription of pro-inflammatory IL-6, IL-11, IL-1α, IL-1β and COX2 genes." (PMID 24804649, 2014). "When cell lines from IL-1α KO mice were injected into mice, progressive tumor growth occurred, due to the pro-invasive and immunosuppressive effects of tumor cell-derived IL-1β and the absence of immunostimulatory effects of tumor cell-associated IL-1α that is missing in these cells." (PMID 23847618, 2013). "Thus, fibrosarcoma cell-derived IL-1α and IL-1β do not act in concert and each IL-1 molecule has unique effects on tumor invasiveness or on anti-tumor cell immune responses." (PMID 23847618, 2013). "The levels of GM-CSF, IL-1α, and IL-1β were not altered in the tumor following radiation therapy." (PMID 23936036, 2013). "Except for IL-1β at week 5, host-derived cytokines levels did not significantly differ between the tumor-free and the SiHaCDV cohorts at any time point post-inoculation of the cells, pointing to a markedly diminished host inflammatory response compared to SiHaparental xenografts." (PMID 24325392, 2013).
tumor (continued). "Thus, in mice bearing tumors of IL-1β secreting cells, anti-tumor cell specific immunity is activated, due to the adjuvant-like effects of IL-1β; however, protective immunity is not manifested, due to suppression of immune effector mechanisms." (PMID 23847618, 2013). "As these factors are identical to those produced from human MM during the initial stages of inflammation in a SCID mouse MM xenograft model, we believe that IL-1β may be responsible for MM tumor progression also in absence of asbestos fibers." (PMID 23937860, 2013). "The outgrowing tumours indeed contain a mixture of IL-1β expressing and non-expressing cells." (PMID 23065753, 2012). "Our data indicate that IL-1β enhances the pro-inflammatory response by suppressing TGF-βsignaling through TRAF6-mediated sequestration of TβRIII, which may be an important contributor to the early stages of tumor progression." (PMID 22427868, 2012). "In addition, tumour growth and recurrence are inhibited by IL-1β, rather than pro-IL-1β, suggesting that cleavage of pro-IL-1β to IL-1β by the inflammasome is critical for tumour suppression." (PMID 23065753, 2012). "We next tested whether or not IL-1β stimulation affected tumor cell migration using a transwell migration assay lacking a collagen matrix substrate." (PMID 23342250, 2012). "Finally, we demonstrated that HCT116 cells expressing dominant negative TCF4 (dnTCF4) or HCT116 cells with silenced Snail failed to stimulate IL1β production in macrophages, demonstrating that tumor cells activate macrophages via a Wnt-dependent factor." (PMID 23029025, 2012). "To study the effects of pardaxin on tumor functions, we performed a real-time RT-PCR analysis of caspase-3, caspase-7, caspase-8, caspase-9, Bax, Bcl-2, STAT2, ATF3, STAT3, SOCS3, IL-2, cathelicidin, TNF-α, MyD88, NF-κB1, p65, IFN-β1, IFN-γ, IL-1β, IL-6, IL-7r, and IL-10." (PMID 23015777, 2012). "Thus, in order to determine the amount of tumour-derived IL-1β required for inhibition of tumour growth, B16F10-IL-1β and B16F10-vector cells were mixed at different ratios (0:1, 1:64, 1:16, 1:4 and 1:0) to obtain low to high levels of secreted cytokine (0, 17.8, 64.2, 328.6 and 1580.3 pg/ml)." (PMID 23065753, 2012). "IL-1β negative B16F10-vector tumours grew faster in wild-type mice than in Il1r1−/− mice, suggesting that IL-1β produced by inflammatory cells and stromal cells may promote tumour growth." (PMID 23065753, 2012). "Thus, besides the recent reports showing the tumour cytotoxicity of N1 TANs through TGF-β blockade and tumour-entrained neutrophils by CCL2, we identify a new mechanism mediated by IL-1β." (PMID 23065753, 2012). "Because type I collagen degradation requires the enzymatic activity of the MMPs, we tested whether or not IL-1β-induced tumor invasion was MMP-dependent." (PMID 23342250, 2012). "Furthermore, α-TEA treatment modulated the tumor microenvironment in a proinflammatory fashion, as we found significantly higher IL-6 and CCL5 levels and a trend toward higher levels of other proinflammatory mediators (IL-1β, CCL2, CCL3, CCL4)." (PMID 21232138, 2011). "We showed that TNFα and IL-1β also failed to induce c-jun in cells expressing dnTCF4, confirming the importance of Wnt signaling for the biological activity of these cytokines and for the interaction of tumor cells with macrophages." (PMID 20661477, 2010). "Finally, since we demonstrated that macrophages and IL-1β protect from TRAIL-induced apoptosis through Wnt signaling, we tested whether macrophages can protect tumor cells transfected with Snail siRNA from TRAIL-induced apoptosis." (PMID 20661477, 2010). "In tumour supernatants of freshly derived tumours and TDLNs, we could detect all three cytokines IL-1β, -6 and -23 (data not shown)." (PMID 20877351, 2010).
tumor (continued). "Studies have demonstrated that TANs may promote tumor angiogenesis by inducing sustained release of vascular endothelial growth factor (VEGF) from peripheral endothelial cells or by secreting pro-inflammatory and immunosuppressive factors, such as IL-1β, IL-17, TNF-α, CCL4, MMP-9, CXCL8, and ANG1." (PMID 40563367, 2025). "Regarding the cytokine profile, notable modulations were observed in the levels of IL-1β, IL-4, IL-6, IL-10, IL-17A, and TNF-α, particularly in the FMT groups, indicating an influence on the local immune response that could contribute to shaping the tumor microenvironment." (PMID 41614846, 2025). "Additionally, cytokine analysis of sorted splenic Mac1+Gr-1+ myeloid cells from tumor-bearing mice revealed that compared with WT controls, cystatin C deletion significantly increased the expression of proinflammatory cytokines, including TNF-α, IL-1β, and IL-12." (PMID 41233352, 2025). "IL-1β, as opposed to IL-18, may play a dominant role in mediating anti-tumor immunity." (PMID 38391959, 2024). "Additionally, studies in rats have found that Nesfatin-1 can inhibit cell apoptosis induced by IL-1β inflammation and promote angiogenesis by inhibiting neutrophil recruitment, cell apoptosis, and activating VEGF, mechanisms that can indirectly promote tumor bone metastasis." (PMID 38571500, 2024). "Based on scRNA-seq analysis and in vitro experiments, Aiko showed that high levels of IL-1β in TME may cooperate with IFN-γ to induce up-regulated expression of PD-L1 in tumor cells through activation of MAPK signaling, which in turn leads to resistance to tumor immunosuppression." (PMID 39144829, 2024). "Thus, whether the IL-1β released during GSDME-mediated pyroptosis is proteolytically matured or not remains unclear and warrants further investigation as this would reveal important insights into the tumor microenvironment." (PMID 38391959, 2024). "Also, the increase in IL-1β secretion along with the simultaneous decrease in TGF-β1, IL-10, and CD206 levels suggest that the COX-2 inhibition could redirect macrophages towards a pro-inflammatory, anti-tumor M1 phenotype, opposing the effects of TMZ." (PMID 38334650, 2024). "We found that concentrations of both IL-6 and TNFα were significantly high in the matched non-tumor and the matched tumor groups than healthy people (H) (P = 0.0289 and P < 0.001 for IL-6, and P = 0.001 and P < 0.001 for TNFα, respectively), whereas IL-1β was not (P = 0.7156 and P > 0.9999)." (PMID 38166062, 2024). "This reduction in MCP in Il1b–/– tumors is not apparent relative to WT mice, which might reflect that IL-1β–producing BMDMs are restricted to perinecrotic/perivascular areas of tumors and the ELISA was performed on whole-tumor lysates." (PMID 37733448, 2023). "Also, chrysin has been found to reduce EAC tumor size through inhibiting VEGF and inflammatory molecules involved in angiogenesis, suppressing DNA topoisomerases, and histone deacetylase, as well as downregulating tumor necrosis factor α (TNF-α) and interleukin 1β (IL-1β)." (PMID 36905557, 2023). "Prior studies have noted the ability of CAAs in secreting high abundance of IL-6, IL-1β, CCL2, chemokine (C–C motif) ligand 5 (CCL5), tumor necrosis factor-α (TNF-α), vascular endothelial growth factor (VEGF) and leptin, which could enhance tumor invasion and immune escape." (PMID 37127625, 2023). "Similarly, in this study, the tumor tissue sections showed an obvious inflammatory reaction, and changes in the mRNA expression levels of inflammatory response pathway-related molecules and first responders of inflammation, such as NF-κB, TNF-α, and IL-1β, were detected." (PMID 37630266, 2023). "However, unlike our observations in tumor cells, the expression of IL-1β, PTGS2, and their receptors was positively regulated by piperine in HaCaT cells, indicating the pro-inflammatory action of non-tumor cells against this molecule, which can be considered a stress stimulus." (PMID 36678600, 2023).
tumor (continued). "Similarly, therapeutics targeting mMSDCs (fludarabine) versus gMDSCs (anti-IL1β) had sex-dependent effects on GBM tumor growth in murine models, with fludarabine treatment decreasing tumor growth solely in males and anti-IL1β treatment decreasing tumor growth solely in females." (PMID 38322284, 2023). "Treatment with DNAase, to a smaller extent, reduced the maturation of IL-1β, but did not inhibit the IL1β release, suggesting that DNA-RNA hybrids present in tumor CM, could be responsible for the IL-1β secretion and inflammasome activation in THP1 macrophages, rather than dsDNA." (PMID 37449203, 2023). "In further support to the upregulation of key effectors for tumour surveillance, lepadin A increased synthesis of IL-6 and reduced the secretion of the immunosuppressive cytokine IL-10 in the supernatants of the co-cultures with DCs, while did not affect the levels of IL-1β and TNFα." (PMID 37779162, 2023). "Moreover, cytokines such as IL-1β and TNF-α have also been reported to be inducers of the inflammatory phenotype in CAFs48, which in turn upregulate the expression of cytokines and chemokines that may further promote tumor growth and proliferation." (PMID 37863888, 2023). "Interestingly, several research groups have documented that lycopene could suppress proinflammatory cytokines such as IL-1, IL-1β, IL-6, and TNF-α in several tumor models, including PCa, by downregulating their production and, thus, preventing the inflammatory state." (PMID 36829848, 2023). "Therefore, we speculate that PMN-MDSC-derived IL-1β may stimulate tumor cells to produce MMP-9 in micrometastatic regions, thereby leading to ECM remodeling and the establishment of a favorable microenvironment for tumor growth." (PMID 35805039, 2022). "Similarly, the release of cytokines such as IL1β downstream of inflammatory caspases may confer anti-tumor immune responses, regardless of whether the majority of tumor cells initially undergo pyroptosis." (PMID 35625711, 2022). "In immune analysis, ICAM1, IL1B, IL-6, MMP1, MMP3, MMP9, and SERPINE1 all showed positive correlations with most immune cells, implying that CC and MF may exert an antitumor activity by interacting with these genes and immune cells, and thus control tumor development." (PMID 35783510, 2022). "Finally, analysis of polysomal RNAs from livers of CTL and TIA1 knockdown LPTENKO mice indicated that consistent with a lack of effect of TIA1 downregulation on tumor growth and progression, markers for proliferation (Mki67, Pcna, Cdkn1a, Cdkn1b, Cdc25a) and inflammation (Il1b, Tgfb) were unchanged." (PMID 35406476, 2022). "The release of inflammatory factors, including IL-1β, IL-1 receptor antagonist, IL-8, IL-10, and tumor necrosis factor-alpha (TNF-α) changes the adhesion of gastric mucosal cells, which leads to the migration and diffusion of tumor cells without mutations of tumor suppressor genes." (PMID 36185234, 2022). "In addition to IL-1β, other strategies have been proposed, namely the delivery of oxygen to attenuate the hypoxic TME or the delivery of alkaline buffers to control TME pH, or even collagenases and hyaluronidase to allow for tumor ECM penetration of other therapeutic agents." (PMID 36180901, 2022). "However, several pro-inflammatory cytokines, including IL-1β, IL-6, and IL-17, are blocked by infliximab stimulation or combined treatment of infliximab and TNF-α, which indicates that anti-TNF-α treatment might modulate tumor-influenced inflammation in HCC." (PMID 34948424, 2021). "Interestingly it has also been demonstrated that, in murine invasive breast cancer models, the absence of a functional NLRP3 impaired tumor growth, and NK cell depletion abolished the anti-tumoral effect independently from effector mechanisms of IL-1β and IL-18." (PMID 33840390, 2021).